C3AR1 (complement C3a receptor 1)
Diseases named in the same sentence as C3AR1 in open-access papers (continued):
Sharing a sentence is not in itself a finding about the gene and the disease.
scrapie (1 paper, 2018). A fatal disease of the nervous system in sheep and goats, characterized by pruritus, debility, and locomotor incoordination. "To assess the influence of these individual innate immune receptors on CNS prion pathogenesis, we used ic inoculation of 22L scrapie in mice deficient in TLR2 (Tlr2-/-), C3aR1 (C3ar1-/-), or C5aR1 (C5ar1-/-)." (PMID 30596651, 2018).
soft tissue sarcoma (1 paper, 2021). A malignant neoplasm arising from muscle tissue, adipose tissue, blood vessels, fibrous tissue, or other supportive tissues excluding the bones. "C3AR1 may predict chemotherapy resistance and outcomes of soft tissue sarcomas." (PMID 33748161, 2021).
thoracic aortic aneurysm (1 paper, 2022). An aneurysm formed in the wall of the proximal portion of the descending aorta proceeding from the arch of the aorta. "In addition, the expression of C3AR1 has been suggested to be associated with the formation of thoracic aortic aneurysms." (PMID 36712250, 2022).
triple-negative breast carcinoma (1 paper, 2020). An invasive breast carcinoma which is negative for expression of estrogen receptor (ER), progesterone receptor (PR), and human epidermal growth factor receptor 2 (HER2). "Additionally, we explored TCGA data and analyzed the correlation between C3aR1+PDGFA+ expression and the survival of triple negative breast cancer patients, we found that patients with a high level of C3aR1+PDGFA+ expression had a poorer survival rate." (PMID 31931851, 2020).
tularemia (1 paper, 2025). Tularemia is an infection caused by the bacterium Francisella tularensis. "The observation, by us and others, that WT and C3-/- mice have similar susceptibility to tularemia while C3ar1-/- mice are clearly less resistant is puzzling." (PMID 41406154, 2025). "We showed for the first time that mice deficient in C3aR1 and CR2, but not C3 or C5aR1, were more susceptible to tularemia." (PMID 41406154, 2025).
Ureteral obstruction (1 paper, 2021). Obstruction of the flow of urine through the ureter. "Studies have found that the synthesis of complement C3 in renal tubular epithelial cells of mice with unilateral ureteral obstruction increases, and the expression of complement receptor C3AR1 in mesenchymal cells increases." (PMID 34735495, 2021).
tumor (125 papers, 2014 to 2026). "The C3AR1 and C3a signaling axis is well documented in enhancing tumor metastasis via manipulating the tumor-associated fibroblasts." (PMID 37511575, 2023). "We used multi-omics approaches to evaluate the association of complement signature C3/C5/C3AR1/C5AR1 with tumor immune phenotypes and prognosis across various cancer types." (PMID 34439277, 2021). "The additional mutational analysis on the 20 linker genes, including C3AR1, showed a significant amplification frequency across tumor samples." (PMID 31879572, 2019). "Furthermore, the tumor cells that were positive for C3AR1 scored high for signatures associated with inflammation, as well as several pathways associated with cell cycle regulation." (PMID 39172519, 2024). "In addition, increased C3AR1 expression predicted more infiltration of tumor-associated macrophages, dendritic cell and CD8 + T cell." (PMID 37005667, 2023). "Moreover, C3a, which binds to an orphan G protein-coupled receptor encoded by C3AR1, was reported as an immune regulator in the tumor microenvironment and act as insidious propagators of tumor growth and progression." (PMID 33604283, 2020). "CD8+ T cell function is enhanced by reducing tumor growth in C3aR1KO mice, indicating that C3aR1 and C5aR1 regulate cytolytic activity of tumor-infiltrating lymphocytes (TILs)." (PMID 40309765, 2025). "Crucially, C3AR1 is positively correlated with 18 tumor metastasis related genes including FN1, SNAI2, and ZEB2." (PMID 37005667, 2023). "Results showed that elevated C3AR1 was significantly related to multiple malignant characteristics, including tumor grade, stage, days to new tumor event, lymph node metastasis, cancer status, and survival status." (PMID 37005667, 2023). "C3AR1 protein levels in tumor sample tissues were higher than that in normal tissues, which were mainly distributed in the membrane and cytoplasm of cancer cells." (PMID 37005667, 2023). "A multi-omics analysis has found an association between C3/C5/C3AR1/C5AR1 and tumor immune evasion and therapy response in several types of cancer." (PMID 37628784, 2023). "In our current research, we use comprehensive bioinformatics analysis to explore the expression and clinical value of C3AR1 in OC, and further explore its regulatory network and its role in shaping the tumor immune microenvironment." (PMID 37005667, 2023). "C3AR1 expression was positively correlated with chemokines and their receptors in the tumor microenvironment, such as CCR1(R = 0.83), IL10RA (R = 0.92), and INFG (R = 0.74)." (PMID 37005667, 2023). "C3AR1 expression was also correlated with lymphocyte-mediated tumor killing and a tumor’s sensitivity to immunotherapy." (PMID 37907575, 2023). "Results show that C3AR1 has the strongest correlation with M2 macrophages (CD163, MRC1, CD209), tumor-associated macrophages (CCL2, CD86, CD68) and monocyte immune markers, including (CD14, CD33, ITGAX)." (PMID 37005667, 2023). "Immune and stromal cell populations included 2 populations: Macrophages 1 (c1: C1qa, C1qb, C3aR1, Cd68, Csf1r, Tlr2, and Cd86) and 2 (c6 + c9: Ccr7, Csf2rb, Il1b, and Cd74) expanded in PNs as a percentage of total tumor cells." (PMID 36134665, 2022). "In agreement with a previous study, our analysis revealed a context-dependent association between C5, C3, C3AR1, and C5AR1 expression and tumor immune infiltration across different cancer types." (PMID 34439277, 2021). "On the TIMER and THPA websites, it is verified that the expression levels of CYBB, CD86, and C3AR1 genes in tumor tissues were higher than those in normal tissues." (PMID 34950700, 2021). "We identified and verified that the expression levels of CYBB, CD86, and C3AR1 in tumor tissues were higher than those in normal tissues." (PMID 34950700, 2021). "Further analysis revealed that C3, C5, C3AR1, and C5AR1 were associated with tumor immune evasion via dysfunctional T-cell phenotypes with a lesser contribution of T-cell exclusion." (PMID 34439277, 2021).
tumor (continued). "Our results suggest that C3, C5, C3AR1, and C5AR1 are associated with tumor immune evasion via dysfunctional T-cell phenotypes with a lesser contribution of T-cell exclusion." (PMID 34439277, 2021). "Further correlation analysis revealed that C3, C5, C3AR1, and C5AR1 were associated with tumor immune evasion via dysfunctional T-cell phenotypes with a lesser contribution of T-cell exclusion." (PMID 34439277, 2021). "We explored the relationships between CNAs of the complement component and the tumor immune microenvironment by examining the correlations between CNAs of C3 C5, C3AR1, C5AR1, and dysfunctional T-cell phenotypes in TCGA cancer cohorts." (PMID 34439277, 2021). "Our results demonstrate that the expression levels of C3, C3AR1, and C5AR1 were inversely associated with tumor purity." (PMID 34439277, 2021). "C3, APP, GAL, and C3AR1 have also been shown to be involved in the regulation of cancer cell metastasis and tumor invasion in multiple cancers." (PMID 34239596, 2021). "Analysis of differential gene expression at different tumor stages revealed an association between tumor stages and high gene expression of C3 in THCA and KIRC; C3AR1 in SKCM; and C5AR1 in BLCA, THCA, and SKCM." (PMID 34439277, 2021). "Lastly, we also demonstrated that the expression levels of C3, C5, C3AR1, and C5AR1 were associated with context-dependent chemotherapy, lymphocyte-mediated tumor killing, and immunotherapy outcomes in different cancer types." (PMID 34439277, 2021). "Collectively, these correlation analyses established a strong association between C3, C5, C3AR1, and C5AR1 and tumor immune evasion via dysfunctional T-cell phenotypes with a less significant contribution from T-cell exclusion." (PMID 34439277, 2021). "We found that LGALS9_CD44, MIF_TNFRSF14, CD47_SIRPG, MDK_LRP1 and LGALS9_HAVCR2, CD74_COPA, C3_C3AR1, ANXA1_FPR3 interactions were upregulated in both ductal-tumor and malignant cells versus ductal-normal." (PMID 35087839, 2021). "Overall, our differential expression analysis suggests tumor context and stage-dependent heterogeneity in the expression of complement components C3, C5, C3AR1, and C5AR1 in different cancer types." (PMID 34439277, 2021). "C3, C3AR1, and C5 participate in the genesis and development of multiple tumor types, while their effects on ccRCC remain obscure." (PMID 34688260, 2021). "Compared to others, there was a distinct difference in C3AR1 expression between primary tumor sites." (PMID 33748161, 2021). "An interaction between C3AR1 and IL10 has been shown previously in another type of immune cell; C3AR1 inhibited IL10 production by CD8+ tumor-infiltrating lymphocytes." (PMID 33176797, 2020). "To date, the understanding of the roles of NMRGs in immunomodulation remains limited, with preliminary preclinical findings suggesting the involvement of EDNRB and C3AR1 in modulating immune escape, and immune cells infiltration to tumour microenvironment in GBM." (PMID 41301734, 2025). "C3AR1 is highly expressed in GBM and is associated with aggressive tumor growth." (PMID 39172519, 2024). "In addition, multiple components of the complement system, a central mediator of RT-induced tumor-specific immunity, were upregulated — specifically, C1qa, C1qb, C1ra, C1s1, C3, C3ar1, C4b, and C6." (PMID 37345658, 2023). "The enrichment analysis of DEGs and co-expressed genes of C3AR1 are highly consistent, indicating that C3AR1 may be related to tumor immune cells or immune regulation." (PMID 37005667, 2023). "C3AR1 was reported in driving tumor immunity in multiple cancers." (PMID 37005667, 2023). "MCP counter analysis showed that patients have higher C3AR1 tend to have more tumor immune cell infiltration, including T cells, cytotoxic lymphocytes, B lineage, NK cells, monocytic lineage, myeloid dendritic cells, neutrophils, endothelial cells and fibroblasts (P < 0.01)." (PMID 37005667, 2023).
tumor (continued). "We speculate that C3AR1 may be involved in m6A-related gene-mediated tumor regulation, and its tumor-promoting effect may be achieved through the modulation of WTAP." (PMID 37005667, 2023). "We observed that MFAP5 + fibroblasts were the main senders that could release complement C3 to interact with the receptors ITGAM/ITGB2, ITGAX/ITGB2, and C3AR1 of C1QC + macrophages in tumor tissues, thus activating the complement system." (PMID 37344903, 2023). "We found that the mRNA expression of C1QA, C1QB, C1QC, C5AR1, C3AR1, C1QR (CD93), CR1, CR2, CR3 (ITGAM), and CR4 (ITGAX) were positively associated with almost all kinds of tumor immune cells, including CD8+ T cells, CD4+ T cells, B cells, macrophages, monocytes and DCs." (PMID 34813686, 2022). "We speculated that C3AR1 may play a similar role in tumor immunity and promoting the development of ESCC." (PMID 34926275, 2021). "Intriguingly, the deficiency of C3aR1, C5aR1, or C5aR2 generated opposite results to the deficiency of C3, with a modest increase in tumor number and growth, whereas the MAC did not play a key role either way." (PMID 32682912, 2021). "Further, our correlation analysis suggests that these associations between the expression levels of C3, C3AR1, and C5AR1 and tumor immune infiltration could possibly enhance tumor immune evasion via dysfunctional T-cell phenotypes." (PMID 34439277, 2021). "C3, FN1, and C3AR1 are overexpressed in multiple tumor cell lines." (PMID 34688260, 2021). "In this respect, the down-regulation of C3AR1 might inhibit the process of tumor growth and progression." (PMID 33604283, 2020). "C3AR1 is an oncogenic gene that down regulates in tumour cells." (PMID 31879572, 2019). "Additionally, the C3a secreted from the tumors could also engage with C3aR1 in the tumor microenvironment to promote NLRP3 inflammation-induced metastasis." (PMID 38894892, 2024). "Also, there was a closely correlation between C3AR1 mRNA and immune cells, indicating that C3AR1 mRNA could be involved in regulation of tumor immune microenvironment." (PMID 33748161, 2021). "Furthermore, high expression levels of C3, C5, C3AR1, and C5AR1 are significantly (p < 0.05) associated with tumor subtypes in KIRC, LUAD, LUSC, and STAD, while tumor stages of BRCA are significantly (p < 0.05) associated with the expression of C3, C5, and C5AR1." (PMID 34439277, 2021). "In a murine model resistant to ICI, inhibitors of C3aR1 (SB290157) and C5aR1 (PMX53) reduced tumor growth and TIL function, increasing IFN-γ production." (PMID 40309765, 2025). "In this study, we demonstrate that C3, C3AR1, and C5AR1 are robustly expressed in GBM cells, indicating potential tumor cell-specific functions of these complement components." (PMID 40843669, 2025). "Although accumulating evidence agrees on the pro-tumoral role of C5, C3, C3AR1, and C5AR1, the immune infiltration is largely controlled by the properties of the tumor cells themselves." (PMID 34439277, 2021). "For validation, qRT-PCR of an ESCC patient cDNA microarray was performed, and demonstrated that C1QA, C3AR1, LCP2, SPI1, and TYROBP were up-regulated in tumor samples and predict poor prognosis." (PMID 34926275, 2021). "Here, we synthesise advances in intracellular and extracellular complement, with emphasis on complement component 3 (C3) and receptors (C3aR1, C5aR1/CD88, C5aR2/C5L2), highlighting how these pathways shape T-cell metabolism, exhaustion programmes and inflammatory tone within tumours." (PMID 41719156, 2026). "Mice treated with C3aR1 (SB290157) and C5aR1 (PMX53) inhibitors had reduced tumor growth." (PMID 38339243, 2024). "We speculate that the overexpression of C3AR1 promotes the infiltration of TAM cells and M2 macrophages in OC, thereby accelerating tumor progression." (PMID 37005667, 2023). "The role of C3AR1 in tumor cells is not yet verified; although, its expression is associated with low survival rate in some cancers, as depicted by the Human Protein Atlas." (PMID 37511575, 2023).
tumor (continued). "Additionally, the analysis showed that C1QA, C3AR1, LCP2, SPI1, and TYROBP were up-regulated in tumours with the worst prognosis." (PMID 35743646, 2022). "In addition, high levels of HCST, C3AR1, GBP4, LY96, ANKRD22, FPR3 and FCGR2A, have also been related to immune activation and/or inflammatory response in tumours; however, their role in basal-like breast malignancies are yet to be uncovered." (PMID 28351365, 2017). "Similarly, blocking of a subset of TAMs positive for C3AR1, CXCR4, and CSFR1, using either anti-C3a therapy or SB290157 treatment of B16 melanoma mice, resulted in reduced F4/80 infiltration as well as slowed tumor growth." (PMID 39172519, 2024). "In this study, we found that SUCNR1, C3aR1, C5aR1, MMP14, THBS 1, TSP-1, and TREM2, which are abnormally expressed in tumor tissue in situ, may be potentially associated with lymph node metastasis." (PMID 37744272, 2023). "However, the association between C3, C5, C3AR1, and C5AR1 expression and tumor infiltration of MDSCs and TAMs was not statistically significant and, in most cases, an inverse association was found." (PMID 34439277, 2021). "In particular, C3aR1, C5aR1, MMP-14, THBS1, and TREM2 were abnormally highly expressed in orthotopic tumor tissue but were not expressed in lymph node metastasis-negative tissues." (PMID 37744272, 2023). "Therefore, our correlation analysis does not support the role of C3, C5, C3AR1, and C5AR1 in regulating tumor infiltration of TAMs and MDSCs and warrants experimental clarification." (PMID 34439277, 2021).
cancer (58 papers, 2014 to 2026). A tumor composed of atypical neoplastic, often pleomorphic cells that invade other tissues. "Among the three cell types promoting T-cell exclusion, MDSCs and the M2 subtype of TAMs are negatively associated with the expression levels of C3, C5, C5AR1, and C3AR1, while only C3 expression shows a positive association with cancer-associated fibroblasts." (PMID 34439277, 2021). "Similarly, C3a receptor 1 (C3aR1) stable shRNA-mediated knockdown (2 shRNA targeting sequences) prevented the induction in cancer cell proliferation caused by incubation with adipocyte-conditioned media compared with control shRNA–transduced cells." (PMID 39964754, 2025). "Interestingly, deficiency of C3aR1, C5aR1, or C5aR2 produced effects opposite to those observed with C3 deficiency, underscoring the complexity of complement receptor signaling in cancer." (PMID 41300283, 2025). "C3AR1 expression was associated with higher resistance of cancer cells to denileukin diftitox ontak, isotretinoin, carmustine, estramustine, fluphenazine, nelfinavir, megestrol acetate, alectinib, cyclophosphamide, lomustine, and dromostanolone propiona, among others." (PMID 35982458, 2022). "Interestingly, these cancers are among the most mutated cancer types with respect to C3, C5, C3AR1, and C5AR1." (PMID 34439277, 2021). "We found that C3AR1 expression is higher in GBM as compared with all other cancers analyzed in TCGA, whereas Complement Receptor 1 (CR1), CR2, C1qR1 (CD93), and C5AR1 were expressed at varying levels." (PMID 39172519, 2024). "Among the gene signatures, C3 and C5 are the most frequently mutated, while C3AR1 and C5AR1 are less frequently mutated across the cancer types." (PMID 34439277, 2021). "Our analysis of the single nucleotide variation in the gene signature revealed that C3, C5, C3AR1, and C5AR1 have mutation frequencies of 41%, 24%, 14%, and 9%, respectively, across the TCGA cancer types." (PMID 34439277, 2021). "We conducted a gene pathway activity and interaction network analysis to identify the effect of the complement component genes C3, C5, C3AR1, and C5AR1 on 10 major functional and signaling pathways associated with human cancer." (PMID 34439277, 2021). "We found that C3, C5, C3AR1, and C5AR1 were frequently mutated (9~41%) in the studied cancer cohorts." (PMID 34439277, 2021). "We queried the effect of CNVs and differential methylation levels of C3/C5/C3AR1/C5AR1 on T-cell dysfunction phenotypes across the TCGA cancer types." (PMID 34439277, 2021). "Our data confirmed that C3AR1 mRNA and protein were both lowered in cancer than normal tissue specimens (both p < 0.0001)." (PMID 33748161, 2021). "Formerly, C3AR1 was considered to be involved in the innate immune response but is now regarded as a factor in cancer." (PMID 31879572, 2019). "Similarly, C3aR1 knockdown or pharmacological inhibition blocked cancer cell proliferation induced by incubation with adipocyte-conditioned media." (PMID 39964754, 2025). "Upregulation of Serping1 (2.74-fold) and complement component 3a receptor 1 (C3ar1, 2.24-fold) demonstrated dynamic regulation of the complement system, which might be related to cancer cell apoptosis, nodule formation and MOF trafficking." (PMID 38887543, 2024). "Similarly, CD8+ T-cell infiltrations correlate strongly (r = 0.5~<0.7) with C3AR1 in 11 cancer types (SKCM, SKCM-Primary, SKCM-Metastasis, STAD, BRCA, HNSC, HNSC-HPVneg, LUSC, PAAD, BRCA-Her2, and BRCA-Luminal)." (PMID 34439277, 2021). "We found that the complements C3, C5, C3AR1, and C5AR1 have deregulated expression in human malignancies and are associated with activation of immune-related oncogenic processes and poor prognosis of cancer patients." (PMID 34439277, 2021). "We found that C3, C5, C3AR1, and C5AR1 expression is negatively associated with infiltrations of M2-TAMs and MDSCs but positively associated with CAF infiltrations in various cancer types." (PMID 34439277, 2021).